FDPS (farnesyl diphosphate synthase)
Diseases named in the same sentence as FDPS in open-access papers (continued):
Sharing a sentence is not in itself a finding about the gene and the disease.
colon cancer (8 papers, 2018 to 2025). "FDPS is mainly known to mediate immunoregulatory functions, its activity and expression have been also documented in human colon cancer and certain other neoplastic disorders." (PMID 32375652, 2020). "Comparative proteomic analysis of murine CAFs isolated from sporadic colon cancer with their matched normal fibroblasts revealed upregulation of latent transforming growth factor beta binding protein 2 (LTBP2), farnesyl diphosphate synthase (FDPS), and cadherin 11 (CDH11) in CAFs." (PMID 29280568, 2018). "We examined the expression of several key cholesterol biosynthetic enzymes (HMGCR, FDPS, and SQLE) in paired colon tumor and non-tumor tissues performed by western blot and immunohistochemistry analysis." (PMID 34621019, 2021).
breast carcinoma (6 papers, 2020 to 2025). "In this study, we show that gene expression of FDPS has a causal relationship with breast cancer." (PMID 36634566, 2023). "Certainly, high levels of FDPS mRNA along with of the transcripts of isoprenoid pathway genes have been associated with poor prognosis and decreased survival rate in a six microarray datasets meta‐analysis of primary breast cancers." (PMID 32596949, 2020). "The overexpression of GGPS1, FDPS, and GART in breast cancer was also associated with a highly significant overall reduction in the survival of patients with breast cancer compared with that of patients without overexpression of these cellular molecules." (PMID 33670680, 2021). "To exemplify the usefulness of the findings presented here, we focused on breast cancer and demonstrate that targets of bisphosphonates such as FDPS and GGPS1 as well as statin such as HMGCS1 are excellent fitness genes in breast cancer and many hard-to-treat cancers." (PMID 33670680, 2021). "GGPS1 and FDPS are targets of nitrogen-containing bisphosphonates such as zoledronic acid derivatives that are widely used to prevent bone-related events related to breast cancer relapse." (PMID 33670680, 2021). "The significance of the overexpression of GGPS1, FDPS, and GART in the pathophysiology of breast cancer is also evident by the fitness dependency of breast cancer cells on these genes." (PMID 33670680, 2021). "However, the nature and context of cellular targets of bisphosphonates in breast cancer (GGPS1 and FDPS) are expected to be different from its targets in bone." (PMID 33670680, 2021). "The levels of GGPS1, FDPS, and GART were significantly elevated in breast tumors as compared to matching adjacent normal tissues, breast cancer cell lines, breast cancer subtypes, and triple negative breast cancer (TNBC) compared with the normal adjacent tissue or non-TNBC tumors." (PMID 33670680, 2021).
ovarian carcinoma (6 papers, 2017 to 2025). A malignant neoplasm originating from the surface ovarian epithelium. "Numerous previous studies have shown that FDPS is strongly associated with tumor drug resistance (For example, FDPS modulates platinum sensitivity in human ovarian cancer; Disruption of the FDPS/Rac1 axis increases the sensitivity of radiation therapy for pancreatic ductal adenocarcinoma)." (PMID 40839681, 2025).
pancreatic cancer (6 papers, 2018 to 2025). "A recent study has showed that various enzymes involved in cholesterol biosynthesis, including FDPS, were associated with radioresistance in pancreatic cancer cells." (PMID 31993371, 2019). "Through global transcriptomic data analysis (PAAD), we found that FDPS transcript levels are significantly higher in pancreatic tumours than in normal pancreas." (PMID 34971971, 2022). "In particular, the knockdown of FDPS, which was overexpressed in human pancreatic cancer tissue, or its pharmacological inhibition through zoledronic acid, radiosensitized pancreatic cancer cells, suggesting that cholesterol synthesis is crucial for radioresistance." (PMID 31993371, 2019). "Additionally, the overexpression of GGPS1, FDPS, GART, and 3-hydroxy-3-methylglutaryl-CoA synthase 1 (HMGCS1) was also associated with a highly significant overall reduction in the survival duration of patients with esophageal and pancreatic cancers." (PMID 33670680, 2021).
hepatocellular carcinoma (4 papers, 2019 to 2026). A malignant tumor that arises from hepatocytes. "The results showed that MY019(FC ≈ 2.0), DNA2(FC ≈ 2.3) and FDPS(FC ≈ 1.9) were significantly highly expressed in the human hepatocellular carcinoma cell line Hep3B2.1-7 compared to LO2 in normal human hepatocytes (P < 0.05)." (PMID 40839681, 2025). "HTyr showed the antiproliferative and proapoptotic effects by inhibiting the lipogenic enzymes fatty acid synthase (FAS) and farnesyl diphosphate synthase (FPPS) in human hepatoma cells, whose higher levels may be related with aggressive behavior of tumor." (PMID 31137753, 2019).
virus infection (4 papers, 2016 to 2025). "The mRNA expression of these five genes, HMGCS1, HMGCR, MVD, MVK, and FDPS, was consistently decreased after M1 virus infection in both HCT-116 and SW1990 cell lines." (PMID 29670091, 2018). "Genes controlling the key steps in cholesterol biosynthesis, such as FDPS, ACAT2, MVD, LSS, and FDFT1, were transcriptionally commonly suppressed upon viral infection at 48 hpi." (PMID 40857262, 2025). "DEGs involving in virus infection were observed in the PPI network including CREB3L1, FDPS and IRS2, in which CREB3L1 was reported to be associated with iCell hepatocyte (induced pluripotent stem cell derived hepatocytes from Cellular Dynamics International) susceptibility to HBV infection." (PMID 26900848, 2016).
colorectal cancer (3 papers, 2018 to 2021). A primary or metastatic malignant neoplasm that affects the colon or rectum. "We analyzed the correlation between stemness markers and cholesterol biosynthesis genes in TCGA colorectal cancer (COADREAD) cohort and revealed positive correlations between CSC markers (EphB2 and CD44) and cholesterol biosynthesis genes (HMGCR, HMGCS1, FDPS, and FDFT1)." (PMID 34621019, 2021).
endometrial cancer (3 papers, 2021 to 2026). Primary or metastatic malignant neoplasm involving the endometrium (mucous membrane that lines the endometrial cavity). "Histological and cellular analyses revealed that FDPS is highly expressed in human endometrial cancer tissues and in the endometrial cancer cell line Ishikawa, where it contributes to cell proliferation." (PMID 41683980, 2026). "This study provides new insights into the potential function of FDPS in the uterus and suggests that targeting FDPS may represent a promising therapeutic strategy for endometrial cancer." (PMID 41683980, 2026). "Although FDPS expression has been reported in various cancers, its role in endometrial cancer remains unclear." (PMID 41683980, 2026).
Hypercholesterolemia (3 papers, 2019 to 2024). An increased concentration of cholesterol in the blood. "In nephrotic rats, the upregulation of the FDPS gene significantly promotes cholesterol biosynthesis, providing a crucial insight into the pathogenesis of hypercholesterolemia associated with nephrotic syndrome." (PMID 39359475, 2024). "Another key enzyme in the mevalonate pathway, farnesyl diphosphate synthase (FDPS), is involved in the conversion of acetyl-CoA to cholesterol; FDPS inhibitors, such as the bisphosphonate alendronate, reduce cholesterol synthesis and are used in the treatment of hypercholesterolemia." (PMID 37817228, 2023).
lung carcinoma (3 papers, 2023 to 2024). "We confirmed the results of iTRAQ by western blotting with protein samples from sensitive and resistant brain and lung cancer cells and demonstrated that NCI677397 markedly increased the expression of FDFT1, HMGCS1, FDPS, and FASN." (PMID 38140768, 2024).
Brain Tumor (2 papers, 2018 to 2019). "Statins —the well-known inhibitors of endogenous cholesterol biosynthesis —reduce the growth of Brain Tumor Initiating Cells (BTICs), where mevalonate pathway genes, including FDPS, are strongly upregulated, through a feed-forward loop between c-Myc and the mevalonate pathway." (PMID 31569395, 2019).
malignant melanoma (2 papers, 2019 to 2022). "Recent studies have highlighted FDPS as a critical determinant of cancer progression and survival in acute myeloid leukemia, melanoma, sarcoma, and PDAC patients." (PMID 34971971, 2022).
brain infarction (1 paper, 2021). Tissue necrosis in any area of the brain, including the cerebral hemispheres, the cerebellum, and the brain stem. "Conversely, transient application of HMG-CoA reductase inhibitor Simvastatin or the farnesyl diphosphate synthase (FPPS) inhibitor Zoledronic acid significantly decreased brain infarction volume in MCAO." (PMID 33901180, 2021).
breast tumors (1 paper, 2021). "We noticed an inverse relationship between levels of MAF upregulation and those of GGPS1 or FDPS, and an almost exclusive expression of MAF and GGPS1 or MAF and FDPS in breast tumors." (PMID 33670680, 2021). "The overexpression of GGPS1, FDPS, and GART mRNAs and their respective proteins was observed in breast tumors, along with the coexpression of GGPS1, FDPS, and GART proteins in several of the same breast tumors (presented as empty blocks)." (PMID 33670680, 2021). "Among these cell fitness molecules, we observed a widespread mRNA overexpression and copy number amplification of Geranylgeranyl pyrophosphate synthase (GGPS1), Farnesyl diphosphate synthase (FDPS), and GART (also known as glycinamide ribonucleotide formyl transferase—(GARFT) in breast tumors." (PMID 33670680, 2021).
Crohn disease (1 paper, 2023). A gastrointestinal disorder characterized by chronic inflammation involving all layers of the intestinal wall, noncaseating granulomas affecting the intestinal wall and regional lymph nodes, and transmural fibrosis. "However, rs6677385 (FDPS expression associated) was associated with secondary traits such as metabolic-related blood urea nitrogen and Crohn's disease." (PMID 36634566, 2023).
gastric cancer (1 paper, 2025). A primary or metastatic malignant neoplasm involving the stomach. "Within this pathway, the roles of farnesyl diphosphate synthase (FDPS), isopentenyl-diphosphate delta isomerase 1 (IDI1), and SQLE in gastric cancer remain largely unexplored." (PMID 39809787, 2025).
Hepatic steatosis (1 paper, 2024). Steatosis is a term used to denote lipid accumulation within hepatocytes. "Zoledronic acid, an inhibitor of FDPS, mitigated hepatic steatosis by suppressing de novo lipogenesis in NAFLD mice." (PMID 39359475, 2024).
hepatoblastoma (1 paper, 2024). Hepatoblastoma (HB) is a malignant hepatic tumor and is the most common pediatric liver cancer. "SREBP-2 and NF-Y can regulate the transcriptional activation of FDPS and thereby regulate the proliferation of hepatoblastoma cells." (PMID 39521858, 2024).
influenza (1 paper, 2016). An acute viral infection of the respiratory tract, occurring in isolated cases, in epidemics, or in pandemics; it is caused by serologically different strains of viruses (influenzaviruses) designated A, B, and C, has a 3-day incubation period, and usually lasts for 3 to 10 days. "Viperin can bind and inhibit farnesyl diphosphate synthase (FPPS), which is essential for isoprenoid biosynthesis, and results in an effect on the formation of lipid rafts which play an important role in inhibiting the egress and release of HIV and influenza." (PMID 27232627, 2016).
lymphocytic leukemias (1 paper, 2017). "Here, we compared the effects of a farnesyl diphosphate synthase inhibitor, zoledronate, and a geranylgeranyl diphosphate synthase (GGDPS) inhibitor, digeranyl bisphosphonate (DGBP), on lymphocytic leukemia cell proliferation and apoptosis." (PMID 28300835, 2017).
osteosarcoma (1 paper, 2023). A usually aggressive malignant bone-forming mesenchymal neoplasm, predominantly affecting adolescents and young adults. "FDPS, an osteoclast farnesyl pyrophosphate synthase, is closely associated with osteosarcoma formation." (PMID 37090691, 2023). "Combining literature reports and our results of bioinformatics and RT-qPCR, we hold that EPHX2 and FDPS are the oncogenes, while GBP1, MMD and ZYX are the anti-oncogene in osteosarcoma." (PMID 37090691, 2023).
parasitic diseases (1 paper, 2021). "Similarly, farnesyl diphosphate synthase (FPPS) in the mevalonate pathway is stated as a potential target for several parasitic diseases." (PMID 33777895, 2021).
postmenopausal osteoporosis (1 paper, 2019). Metabolic disorder associated with fractures of the femoral neck, vertebrae, and distal forearm. "The results of this study show the possible role of allelic combinations of SOST rs1234612, PTH rs7125774, FDPS rs2297480, and GGPS1 rs10925503 gene variants in the individual response to BPs treatment in women with postmenopausal osteoporosis." (PMID 31437227, 2019).
pulmonary fibrosis (1 paper, 2022). Chronic progressive interstitial lung disorder characterized by the replacement of the lung tissue by connective tissue, leading to progressive dyspnea, respiratory failure, or right heart failure. "Together, our findings demonstrate that ZA possesses a mechanism of action targeting FDPS to suppress pulmonary fibrosis, which is distinct from currently employed therapeutic interventions." (PMID 35721132, 2022).
pulmonary hypertension (1 paper, 2022). Increased pressure within the pulmonary circulation due to lung or heart disorder. "We used ibandronate to inhibit the FDPS enzyme in vivo and in vitro to investigate the role of FDPS in pulmonary artery endothelial cell injury in pulmonary hypertension." (PMID 35962329, 2022). "FDPS, a key enzyme in the mevalonate (MEV) pathway, plays an important role in vascular stiffness and angiogenesis, which suggests that it may affect pulmonary hypertension." (PMID 35962329, 2022).
retinoblastoma (1 paper, 2012). A malignant tumor that originates in the nuclear layer of the retina. "In retinoblastoma gene-deficient thyroid tumors, FDPS is overexpressed, leading to increased isoprenylation and activation of N-Ras and induction of the DNA damage response." (PMID 22211244, 2012).
schizophrenia (1 paper, 2020). A major psychotic disorder characterized by abnormalities in the perception or expression of reality. "To determine whether upstream lipid donor synthesis of FPP or GGPP was altered in schizophrenia, we assayed the synthases for these lipid pyrophosphate molecules, FDPS and GPPS1." (PMID 32066669, 2020).
T-cell leukemia (1 paper, 2017). A malignant disease of the T-lymphocytes in the bone marrow, thymus, and/or blood. "Therefore, the use of dual inhibitors of the FDPS and GGDPS enzymes is not likely to result in enhanced inhibition of proliferation with respect to T-cell leukemias." (PMID 28300835, 2017).
uveitis (1 paper, 2020). An inflammatory process affecting a part of or the entire uvea. "The second cluster (C2) of genes was relatively higher expressed in JIA cases without uveitis and contained genes involved in cholesterol biosynthesis and mevalonate pathway (e.g., MVD, FDPS, SEC23A)." (PMID 33042130, 2020).
tumor (46 papers, 2010 to 2026). "The value for genetic modification of tumor cells was demonstrated in our studies but we recognize the potential for alternative approaches based on the same underlying concept of decreasing FDPS enzyme activity in tumor cells." (PMID 36275712, 2022). "When antigen-presenting cells or tumor cells are exposed to nitrogen-containing bisphosphonates (N-BPs), such as zoledronic acid and pamidronate, N-BPs inhibit farnesyl diphosphate synthase (FDPS)." (PMID 39195212, 2024). "Our approach was to improve upon these preclinical results by genetically targeting FDPS to further increase IPP levels in tumor cells and promote their subsequent destruction by Vδ2 T cells." (PMID 36275712, 2022). "Dual targeting of FDPS activity, using LV-shFDPS plus ZA increased tumor suppression but the added benefit of adding ZA was modest compared to what was observed for dual targeting in vitro." (PMID 36275712, 2022). "Corroborating our in vitro findings, HMGCR or FDPS deletion significantly inhibited tumor growth in subcutaneous xenograft assay in nude mice." (PMID 34621019, 2021). "Because the mechanism underlying the responses of Vγ2Vδ2 T cells to PTA was, however, not fully elucidated, we first examined the effect of PTA on the activity of FDPS in tumor cells as a model system, a possible target of PTA, at a molecular level." (PMID 32793196, 2020). "At the same time, low p‐β‐catenin level was found in FDPS knockdown xenograft tumours, as well as, overexpression of FDPS increased the p‐β‐catenin expression in syngeneic tumours." (PMID 32596949, 2020). "The FDPS mRNA and protein levels were higher than those of corresponding adjacent non‐tumour samples by real‐time PCR and Western blotting." (PMID 32596949, 2020). "Accumulation of IPP in tumor cells can be achieved by inhibiting the Farnesyl diphosphate synthase (FDPS), an enzyme downstream of the mevalonate pathway, by aminobiphosphonate compounds such as zoledronate." (PMID 30895167, 2019). "The degree of inhibition of farnesyl diphosphate synthase thereby correlates well with important anti-tumor functions of Vγ9Vδ2 T-cells over various tumor cell lines." (PMID 29725332, 2018). "By inhibiting the activity of farnesyl diphosphate synthase, a key enzyme in the mevalonate pathway, tumor cells show reduced potential for migration, proliferation, and angiogenesis and increased apoptosis." (PMID 24371687, 2013). "Additionally, the study explores two strategies to re-sensitize tumors in the weak anti-tumor effect (WAT) group: utilizing a BTN3A1 agonistic antibody or employing bisphosphonates to inhibit farnesyl diphosphate synthase (FPPS)." (PMID 37770968, 2023). "Lastly, we confirmed that dual targeting of FDPS activity, by reducing mRNA and protein levels plus adding the competitive enzyme inhibitor zoledronic acid, increased the potency for Vδ2 T cells suppression of tumor cell growth." (PMID 36275712, 2022). "Down‐regulation of FDPS was confirmed by Western blotting in the shFDPS tumours." (PMID 32596949, 2020). "In contrast, treatment of tumor cells with aminobisphosphonates allows them to stimulate Vγ2Vδ2 T cells by blocking farnesyl diphosphate synthase (FDPS) (also termed farnesyl pyrophosphate synthase), which leads to the accumulation of its upstream metabolite, IPP." (PMID 28239463, 2017). "Interestingly, compared to tumor-free peripheral (TFB) brain and normal human astrocytes (NHA), FDPS protein expression and enzyme activity were detected at high degree in tumor mass where a correlation with canonical oncogenic signaling pathways such as STAT3, ERK and AKT was also documented." (PMID 29075041, 2017). "The MREs ACAT1, ACAT2, FDFT1, FDPS, HMGCL and PMVK were highly expressed in basal tumor cells and urothelial cells." (PMID 39521858, 2024).